TLR9 (toll like receptor 9)
Diseases named in the same sentence as TLR9 in open-access papers (continued):
Sharing a sentence is not in itself a finding about the gene and the disease.
Autoimmunity (continued). "Aberrant activation of STAT3 due to a gain of functionality might lead to an imbalance of TLR7 and TLR9 response through accelerating integrin signaling pathway, further affecting the development of autoimmunity." (PMID 35345674, 2022). "Overall, TLR8- or TLR9-deficiency decreases the competition with TLR7 for association with UNC93B1 and results to increased TLR7 trafficking and signaling that ultimately leads to autoimmunity." (PMID 36389822, 2022). "NET-bound ALRs may potentiate autoimmunity by activating B cells through either endosomal TLR9-NET DNA interactions, or activation of the B cell receptor, in a manner analogous to that reported for the NET-binding peptide LL37." (PMID 35608258, 2022). "Thus, as soon as it was discovered that TLR7 and TLR9 detect viral and bacterial nucleic acids, various studies deployed to evaluate their role in autoimmunity, predominately by studying experimental mouse models." (PMID 36389822, 2022). "TLR3 appears to exist as a functional receptor on the cell membrane more frequently than other endosomal TLRs, probably because endogenous agonists of TLR7, TLR8, and TLR9 are more abundant than dsRNA in uninfected cells, and therefore surface localization of TLR3 poses a lower risk of autoimmunity." (PMID 33597952, 2020). "TLR9 activation facilitates the development of autoantibodies against dsDNA and ribonucleoproteins, indicating a critical role of this receptor in the activation of B cells in autoimmunity." (PMID 31616406, 2019). "In addition, Tlr9- and Tlr8-double-deficient C57BL/6 mice develop spontaneous signs of autoimmunity such as splenomegaly, autoantibody production, and glomerulonephritis." (PMID 29650017, 2018). "Also, because the DNA-specific TLR9 acts as a negative regulator of autoantibody production, it is unlikely that DNA as antigen drives autoimmunity." (PMID 28955333, 2017). "In addition, co-culture of activated B cells of SLE patients with sema3A reduced the expression of TLR-9 in these B cells, thus suggesting that sema3A is a modulator in reducing autoimmunity." (PMID 25978359, 2015). "Accumulating evidence thus suggests that stimulation of TLRs, i.e., TLR9, can incite autoimmunity in humans, and infections may play a role in triggering disease relapses." (PMID 25333705, 2014). "It has been demonstrated that TLR9 is involved in the development of autoimmunity in SLE patients." (PMID 22948541, 2013). "Our in vitro experiments suggest a mechanism, which could explain how low B-cell levels of Carabin can favour overt autoimmunity after TLR9 activation: Carabin inhibits the molecular crossroad between the BCR pathway and the TLR9 pathway." (PMID 23109291, 2012). "Indeed, it was demonstrated in the present study that the addition of sema3A, in vitro, to B cells of SLE patients, significantly reduced ODN-CpG induced TLR-9 expression in memory B cells, supporting sema3A as a regulator of autoimmunity in SLE." (PMID 22697500, 2012). "Moreover, the TLR9 polymorphism in the present study has been identified to correlate with a higher risk of SLE and GD, indicating that rs352140 is essential for promoting autoimmunity." (PMID 37139337, 2023). "Finally, we discuss the implications of TLR9 subcellular localization in autoimmunity." (PMID 30900780, 2019). "We also discuss how TLR9 signaling may be involved in autoimmunity." (PMID 30900780, 2019). "TLR9 is another endosomal TLR that has been linked to autoimmunity, and a potential role for TLR9 in recognition of Bb DNA may exist (data not shown)." (PMID 24904837, 2014). "However, the role of TLR9 inducing autoimmunity is controversially discussed." (PMID 23016675, 2012). "Upon ligand binding, TLR7 and TLR9 recruit the adaptor MyD88, which initiates a signaling cascade leading to IRF5 activation, which is critical to trigger autoimmunity." (PMID 41178711, 2025).
Autoimmunity (continued). "Numerous studies have implicated TLR7 as the main driver of SLE disease, while both TLR8 and TLR9 have been shown to have more regulatory roles where they contribute to dampening TLR7 signaling and thereby prevent autoimmunity." (PMID 38791389, 2024). "ABCs are known to drive autoimmunity, are enriched for autoantibody specificities, are efficient antigen presenters, and require TLR7 or TLR9 signaling for formation in vitro." (PMID 37606042, 2023). "TLR9 ligation enhanced dendritic cell activation upregulating CD40 and CD80 expression, promoting systemic anti-MPO autoimmunity and T cell recall responses and exacerbating kidney injury." (PMID 36674855, 2023). "Nevertheless, by now it is undoubtedly documented that TLR7 plays a central role in SLE, where both TLR8 and TLR9 restrain TLR7 signaling and thus, can protect from autoimmunity." (PMID 36389822, 2022). "In ANCA-associated vasculitis, TLRs play crucial roles in initiating autoimmunity and inflammation, which are primarily attributed to TLR-2-induced Th17 autoimmunity, while TLR-9 promotes Th1 autoimmunity." (PMID 36366292, 2022). "The importance of this regulation is reflected by the fact that deletion of TLR8 or/and TLR9 in mice or even diminution of TLR8 expression in humans, leads to increased TLR7 signaling and subsequent autoimmunity." (PMID 36389822, 2022). "ABC identified in models of autoimmunity are dependent on BcR, TLR-7, and TLR-9 stimulation, and memory ABC populations are implicated in mediating autoimmunity." (PMID 29632538, 2018). "Evidently, TLR9 and TLR8 inhibit TLR7-mediated autoimmunity and renal inflammation in a synergistic manner." (PMID 29650017, 2018). "Obviously, TLR9 and TLR7 normally compete for endosomal trafficking implying that increased TLR7 signaling driving autoimmunity can outweigh the pro-inflammatory effects of TLR9." (PMID 29650017, 2018). "Collectively, these results suggest a role for TLR9, IFN-γR and T-bet as regulators of anti-erythrocyte autoimmunity and promoters of malarial anaemia during P. yoelii infection, possibly mediated by CD11c+ T-bet+ B cells." (PMID 29101363, 2017). "We profiled purified CD19+ B cells from adults with sIgAD without overt clinical symptoms of autoimmunity, to remove any confounding effects of secondary inflammation, and matched controls at baseline and after TLR9 activation." (PMID 41562052, 2025). "Taken together, the DNA components in CSE-NETs promoted NF-κB-, but not type-I IFNs-, dependent autoimmunity via cGAS/TLR9 in long-term CS-induced COPD." (PMID 38880789, 2024). "Herein, we present evidence that CS-induced NETs-DNA sensed by cGAS and TLR9 in AECs and DCs promotes NF-κB-, but not type-I IFNs, dependent autoimmunity in long-term CS-induced COPD." (PMID 38880789, 2024). "Taken together, these results confirmed our hypothesis that ACK1 promotes TLR4/TLR7/TLR9-induced activation of macrophages and DCs, therefore contributes to the pathogenesis of TLR-mediated inflammation and autoimmunity." (PMID 35669783, 2022). "Therefore, both TLR8 and TLR9 are able to restrain TLR7 and their deletion leads to autoimmunity due to increased TLR7 responses." (PMID 36389822, 2022). "The corollary is that increased TLR7 trafficking in the absence of competition with TLR9 may worsen autoimmunity." (PMID 41178711, 2025). "However, UNC93B1 upregulation may also increase the responsiveness of TLR3, TLR7, TLR8, and TLR9 to their agonists, and conditions that lead to increased UNC93B1 expression may yield autoimmune disorders." (PMID 33597952, 2020). "Considering that dysfunction or dysregulation of TLRs, especially TLR4, TLR7, and TLR9, leads to a series of pathological conditions, we investigated whether ACK1 regulates the activation of the TLR signaling pathway and participates in the pathogenesis of inflammation and autoimmunity." (PMID 35669783, 2022).
Autoimmunity (continued). "The TLR trafficking chaperone UNC93B1, which prevents autoimmunity through the recruitment of syntenin-1, suppresses TLR7 specifically without affecting TLR9." (PMID 33371432, 2020).
malaria (83 papers, 2009 to 2025). Malaria is a serious and sometimes fatal disease caused by a parasite that commonly infects a certain type of mosquito which feeds on humans. "This malaria‐associated fever is believed to be due to toll‐like receptor 9 (TLR9) stimulation by plasmodia DNA, and this helps control the infection by killing the parasite." (PMID 41050847, 2025). "Whereas most of the studies have focused on P. falciparum, we explored here the effects of TLR9 gene polymorphisms on the IgG antibody response against two malaria antigens, PvCSP and PvMSP-119." (PMID 40587574, 2025). "A significant association between TLR9 (T1486C) and severity of malaria is observed in allele model (OR: 1.26, 95% CI: 1.08–1.48, I2 = 0%) or homozygous model (OR: 1.55, 95% CI: 1.08–2.28, I2 = 0%)." (PMID 34217314, 2021). "On the whole, the objective of current study was to assess the role of TLR4 (D299G, T399I) and TLR9 (T1237C, T1486C) in severity or susceptibility of malaria by meta-analysis of data from eligible studies." (PMID 34217314, 2021). "Overall, a significant association between TLR9 (T1486C) and severity of malaria is observed in allele model (OR: 1.26, 95% CI: 1.08–1.48, I2 = 0%) or homozygous model (OR: 1.55, 95% CI: 1.08–2.28, I2 = 0%)." (PMID 34217314, 2021). "For TLR9 (T1237C), the adult group of Asian countries is also significantly associated with severity of malaria in heterozygous model (OR: 2.00, 95% CI: 1.09–3.64, I2 = 39%)." (PMID 34217314, 2021). "TLR9 (T1237C) and severity of malaria was significantly associated in the adult of Asian countries under heterogeneous model." (PMID 34217314, 2021). "Regarding the susceptibility to malaria, TLR9 (T1237C) is significantly associated only with the children group under recessive model (OR: 2.21, 95% CI: 1.06–4.57, I2=85%) and homozygous model (OR: 1.49, 95% CI: 1.09–2.0, I2 = 0%)." (PMID 34217314, 2021). "The association of TLR 4/TLR 9 and severity of malaria was reported in nine studies for TLR9 (T1237C), eight studies for TLR9 (T1486C), ten studies for TLR4 (D299G) and five studies for TLR4 (T399I)." (PMID 34217314, 2021). "For TLR9 (T1486C), the adult group of Asian countries is significantly associated with severity of malaria in allele model (OR: 1.25, 95% CI: 1.02–1.53, I2 = 0%)." (PMID 34217314, 2021). "For other polymorphisms such as TLR9 (T1237C), a significant association with severity of malaria is observed in only heterozygous model (OR: 1.89, 95% CI: 1.11–3.22, I2 = 75%)." (PMID 34217314, 2021). "This study aimed to assess the role of TLR4 (D299G, T399I) and TLR9 (T1237C, T1486C) in severity or susceptibility of malaria by meta-analysis of data from eligible studies." (PMID 34217314, 2021). "For TLR9 (T1237C), a significant association with severity of malaria is observed in in heterozygous model (OR:1.89, 95% CI: 1.11–3.22, I2 = 75%)." (PMID 34217314, 2021). "The TLR9 1174 G/A SNP was linked to rapid disease progression in children with malaria and HIV-infected patients and was also associated with nonresponse to anti-TNF treatment among patients with inflammatory bowel disease." (PMID 32753695, 2020). "Although the role of TLR2 and TLR4 in malaria remain obscure, TLR9 deficient mice were reported to be resistant to PbA-induced cerebral malaria, indicating a role in pathology of TLR9 rather than cerebral malaria protection." (PMID 32944216, 2020). "In contrast, an increase in the concentration of IP-10 in TLR3 and TLR9 stimulations was associated with a decreased risk of clinical malaria occurrence in early infancy." (PMID 30384846, 2018). "In contrast, a higher concentration of IP-10 following TLR3 or TLR9 stimulation was associated with a lower hazard of malaria." (PMID 30454004, 2018). "For example, higher concentrations of GM-CSF and eotaxin following TLR7/8 stimulation, of IL-1β following TLR9 stimulation, and of IL-7 following IL-3 stimulation, were associated with an increased hazard of malaria in the first year of life." (PMID 30454004, 2018).
malaria (continued). "The association of the -1486C/T variant present in the promoter region of TLR9 with Pv-malaria in this study corroborated other observations of association of this SNP with susceptibility to symptomatic and placental malaria caused by P. falciparum." (PMID 28850598, 2017). "Association of the polymorphisms TLR5 R392StopCodon and TLR9 -1486C/T with Pv-malaria and the C/C genotype of the SNP TLR9 -1237C/T with increased parasitemia was observed." (PMID 28850598, 2017). "The data presented in this study suggest an association of polymorphisms TLR5 and TLR9 with Pv-malaria." (PMID 28850598, 2017). "Our observed susceptibility association with TLR9 SNPs parallel previous reports of increased risk of low birth weight in term infants of malaria infected pregnant women carrying the TLR9 T-1486C polymorphisms." (PMID 24312262, 2013). "The CT/CC genotype for the rs20541 SNP in IL13 locus (OR=1.38, 95%CI 1.11-1.76, p=0.003) and the TLR9 rs187084 SNP (additive T, OR=1.23, 95%CI 1.05-1.44, p=0.010) were associated with susceptibility to malaria following univariate analysis." (PMID 24312262, 2013). "Previous studies provided intriguing information about TLR9 SNPs and Malaria severity, the association of TLR9 polymorphisms with altered IFN-γ levels has been suggested to be potential explanation to TLR9 mediated pathogenesis." (PMID 24176007, 2013). "On the other hand, few studies have focussed on the effect of TLR9 polymorphisms on susceptibility to mild malaria." (PMID 22594374, 2012). "Nevertheless, this study has highlighted clearly that the TLR9 gene polymorphisms significantly influence susceptibility to symptomatic malaria." (PMID 22594374, 2012). "In this study, the effect of TLR9 polymorphisms on susceptibility to symptomatic malaria was investigated among Ghanaian children." (PMID 22594374, 2012). "In the present study, healthy Ghanaian children living in an area mesoendemic for malaria transmission were recruited into a prospective cohort study for one year, and the effect of the TLR9 SNPs on susceptibility to symptomatic malaria investigated." (PMID 22594374, 2012). "The TLR9 gene has been associated with the pathogenesis of severe malaria in humans and experimental models." (PMID 23316245, 2012). "In particular, a study across three areas of the Amazon basin found significant associations between TLR-1 and TLR-6 variants with mild malaria, whereas TLR-9 variants were associated with high parasitemia." (PMID 22615793, 2012). "Several studies have focused on the relationship of TLR9 polymorphisms and severe malaria phenotypes, with some reporting positive association." (PMID 22594374, 2012). "Taken together, these findings indicate a significant association of TLR9 gene polymorphisms with symptomatic malaria among Ghanaian children in Dangme-West district." (PMID 22594374, 2012). "It is therefore worthwhile to carry out more studies in areas with different malaria transmission and using a larger sample size, so that the role of TLR9 polymorphisms on different malaria phenotypes can clearly be deciphered." (PMID 22594374, 2012). "The TLR9 gene has been implicated in pathogenesis of severe malaria both in murine model and in humans." (PMID 22594374, 2012). "Assessment of the effect of TLR9 genotypes on the risk of symptomatic mild malaria was carried out by calculating the incidence of malaria, the relative risk and attributable risk for each TLR9 genotype studied." (PMID 22594374, 2012). "For instance, polymorphisms in TLR1, TLR4 and TLR9 are associated with an aggravated clinical status of malaria during pregnancy." (PMID 22096530, 2011). "Both TLR4 Asp299Gly and TLR9 -1486T/C were associated with low birth weight and maternal anaemia in a malaria endemic population." (PMID 19317913, 2009). "Recently, the TLR-9-1486C/T variants was found to be associated with high parasitaemia in a cohort of patients with mild malaria from the Amazonian region of Brazil." (PMID 19284650, 2009).